BMPR2 (bone morphogenetic protein receptor type 2)
Diseases named in the same sentence as BMPR2 in open-access papers (continued):
Sharing a sentence is not in itself a finding about the gene and the disease.
endometriosis (4 papers, 2013 to 2025). The growth of functional endometrial tissue in anatomic sites outside the uterine body. "The results of the conducted research indicate that one of the factors contributing to the survival of ectopic endometrial cells outside of their physiological location may be disorders occurring in women with endometriosis, which are associated with the release of BMPR2 into the peritoneal fluid." (PMID 34680408, 2021). "At the BMPR2/2q33.1 locus, the lead SNPs rs72928925 for endometriosis and rs72928605 for osteoarthritis are both regulating expression (eQTLs) of the BMPR2 gene in blood and oesophageal muscularis." (PMID 40262193, 2025). "It was also observed that, at the third stage of endometriosis, the concentration of BMPR2 demonstrated a statistically significant decrease compared to the concentration in the fluid of women at the second stage of the disease (p <0.0001)." (PMID 34680408, 2021). "The analysis of the results demonstrates a statistically significant increase in BMPR2 concentration in the fluid of women at stage II of endometriosis, compared to the concentration of this receptor in women at stage I (p < 0.0001)." (PMID 34680408, 2021). "It is worth emphasizing that, in women at the first stage of endometriosis, the BMPR2 concentration was the lowest while, in those at the second stage of the disease, the level of the examined receptor reached the highest value." (PMID 34680408, 2021). "The aim of the study was to determine the role of soluble bone morphogenetic proteins, BMP-2 and BMP-7, and their receptors, ALK-1 and BMPR2, in the process of the formation and development of endometriosis." (PMID 34680408, 2021). "BMP-2 and BMP-7 and their soluble receptors, ALK-1 and BMPR2, are involved in the formation of endometriosis." (PMID 34680408, 2021). "The average concentration of BMPR2 in women with endometriosis was 1.87 ng/mL (Q1: 1.27 and Q3: 4.34), and in the reference group, this was 0.87 ng/mL (Q1: 0.55 and Q3: 1.36)." (PMID 34680408, 2021). "It was found that, in the peritoneal fluid of women with endometriosis, there was an increased level of BMPR2 compared to the concentration of this receptor in women from the reference group." (PMID 34680408, 2021). "eQTL analyses highlighted genes affected by shared risk variants, enriched for seven pathways across all four conditions, with three genetic loci shared between endometriosis and osteoarthritis (BMPR2/2q33.1, BSN/3p21.31, MLLT10/10p12.31) and one with rheumatoid arthritis (XKR6/8p23.1)." (PMID 40262193, 2025). "The results of this study suggest that increased concentration levels of BMPR2 in the peritoneal fluid of women with endometriosis may affect the intercellular transmission, involving the ligand and receptor for BMP." (PMID 34680408, 2021). "As a result of the tests performed in the peritoneal fluid of women with endometriosis, a statistically significant increase in BMPR2 concentration in the peritoneal fluid of women with endometriosis was found, compared to the concentration of this parameter in the reference group (p < 0.0001)." (PMID 34680408, 2021). "In addition, increased BMPR2 concentration in the peritoneal fluid of women with endometriosis may indirectly indicate that this receptor is present on cells in the form of a heteromeric complex bound to the soluble ligand." (PMID 34680408, 2021). "As a result, this increases soluble BMPR2 concentration and a decrease in BMP-2 concentration in the peritoneal fluid of women with endometriosis." (PMID 34680408, 2021).
Infertility (4 papers, 2015 to 2024). "Conditional ablation of the BMP type 2 receptor, BMPR2, results in infertility owing to placental defects during mid-to-late gestation." (PMID 34099644, 2021). "BMPR2 activation influences granulosa cell proliferation, BMP15 and GDF9 signaling, and disruptions in this pathway can lead to infertility and reproductive abnormalities." (PMID 38275408, 2024).
lung adenocarcinoma (4 papers, 2016 to 2025). A carcinoma that arises from the lung and is characterized by the presence of malignant glandular epithelial cells. "Review of the Cancer Genome Atlas of 135 primary lung adenocarcinomas revealed only 3 missense mutations and 1 truncating mutation of BMPR2, suggesting BMPR2 could be targeted with small molecules." (PMID 31744505, 2019). "Genetic alterations of BMPR2 are infrequent in lung adenocarcinomas." (PMID 31744505, 2019). "In general, downregulation of ZEB1, RECK, TGFBR2 and BMPR2, as well as upregulation of CDK4, CCNE2, EZH2 and DNMT1 has been shown in lung adenocarcinoma and/or squamous cell carcinoma." (PMID 27588394, 2016).
lung diseases (4 papers, 2020 to 2024). "Based on pathway enrichment analysis, genes altered in BPD blood cells were mainly enriched in cell cycle regulation and arrest (e.g., PPP2CA, RBL2, CENPU, CCNY, CDK6) and pulmonary disorder and developmental disorders (e.g., AGER, ITGA6, CA4, BACH2, IGFBP2, BMPR2, SKI, DAB2)." (PMID 35484630, 2022).
osteoarthritis (4 papers, 2015 to 2025). A noninflammatory degenerative joint disease occurring chiefly in older persons, characterized by degeneration of the articular cartilage, hypertrophy of bone at the margins and changes in the synovial membrane. "Furthermore, miR-324-5p/BMPR2 axis was involved in the regulation of NF-κB signaling in osteoarthritis." (PMID 39546499, 2024). "In addition, excessive BMPR2 expression can prevent osteoarthritis by activating the MAPK/JNK/ERK signaling pathway." (PMID 38538669, 2024). "Specifically, three SNPs were shared with osteoarthritis (BMPR2/2q33.1, BSN/3p21.31, and MLLT10/10p12.31), and one was shared with both osteoarthritis and rheumatoid arthritis (XKR6/8p23.1)." (PMID 40262193, 2025). "In human arthritis, the BMP ligands 2 and 6 and their receptors BMPR1a and BMPR2 were upregulated, while BMP ligands 4 and 5 were downregulated in RA and osteoarthritis (OA) synovium in comparison to normal control samples." (PMID 25889670, 2015).
cardiac hypertrophy (3 papers, 2016 to 2025). "Infusion of Ang II for 2 weeks in mice induces the phosphorylation of Smad1 and Smad5 in the carboxyl-terminal, leading to cardiac hypertrophy, which is inhibited by BMPR2 inhibitor, LDN193189." (PMID 39506064, 2025). "Mice with BMPR2 knockout showed reduced Ang II-induced cardiac tissue growth, demonstrating that Ang II can transactivate BMPR2 to activate Smad1 and Smad5, resulting in cardiac hypertrophy." (PMID 39506064, 2025). "Note that BMPR2 mutation in both mice and humans leads to right ventricular dilation under pressure, rather than hypertrophy, and so Fulton index was not assessed." (PMID 26863209, 2016).
colon cancer (3 papers, 2014 to 2024). "Regarding BMPR2−583, a recent study found BMPR2 germline mutations in unexplained colon cancer cases, including the BMPR2−583 hotspot." (PMID 38473427, 2024).
iron deficiency (3 papers, 2019 to 2024). "Taken together, these data indicate that the cellular HAMP/FPN axis in PASMCs is dysregulated by BMPR2 mutations, leading to intracellular iron deficiency, and elevated ET-1 levels." (PMID 31152133, 2019).
liver disease (3 papers, 2019 to 2022). "In another report, heterozygosity of BMPR2 (a mutation which can separately result in heritable PAH) resulted in worse portal hypertension and increased shunting of eggs to the lungs, similarly worsening the PH phenotype." (PMID 30733718, 2019).
neuroblastoma (3 papers, 2019 to 2025). Neuroblastoma (NB) is the most common solid, extracranial childhood tumor. "Overexpression of BMPR2 inhibits, while short hairpin RNA-mediated knockdown of BMPR2 promotes the cell proliferation and clonal formation of neuroblastoma cells." (PMID 35570745, 2022). "Furthermore, BMPR2 expression levels are downregulated in some cancers, such as colon cancer, human prostate cancer, neuroblastoma, bladder transitional cell carcinoma, squamous cell lung cancer, and LAC." (PMID 35570745, 2022). "In contrast, BMPR2 downregulation promoted the development of neuroblastoma." (PMID 31889906, 2019).
pancreatic cancer (3 papers, 2014 to 2017). "This identified PEAK1, BMPR2, COL4A1 and ZEB1 as ITGA1 co-expressors in pancreatic cancer and suggested that ITGA1 may play a role in regulating TGFβ responses in pancreatic cancer." (PMID 28855593, 2017).
portopulmonary hypertension (3 papers, 2016 to 2023). "Importantly, BMPR2 down-regulation contributes to hyper-proliferative, apoptosis resistant phenotype in PAH pulmonary vascular cells, and BMP9 is deficient in portopulmonary hypertension and is a biomarker for transplant-free survival." (PMID 37087509, 2023).
adenoma (2 papers, 2023 to 2025). A neoplasm arising from the epithelium. "The resultant data analyses of the folliculogenesis genes revealed that Lhr and Ahr mRNA in the sex cord and adenoma phenotype, and Foxl2 and Bmpr2 mRNA in tubulostromal adenomas, were similarly expressed to that in mature GCs, with levels significantly different to the naïve cells." (PMID 37174061, 2023).
allergic asthma (2 papers, 2012 to 2022). A asthma with a basis in a pathological type I hypersensitivity reaction. "In addition to vascular remodeling and PAH, we also assessed AHR in our model since a study reported decreased BMPR2 in the airways of asthmatic patients, providing evidence for a potential role for the BMPR2 pathway in allergic asthma." (PMID 22427841, 2012).
Autoimmunity (2 papers, 2018 to 2022). The occurrence of an immune reaction against the organism's own cells or tissues. "We found increased expression levels in the patients with GD when compared against controls, and this overexpression may support the idea of BMPR2 being related to autoimmunity processes." (PMID 29266775, 2018). "Both NK activation and autoimmunity are linked to BMP signaling, e.g., via an autocrine activation pathway via BMP receptors and BMP ligands in NK cells, which fits our identified target genes BMP1, BMP2, BMP3, BMP7, BMP6, BMPER, BMPR1B, and, most importantly, BMPR2." (PMID 35455956, 2022).
breast tumors (2 papers, 2019 to 2023). "Like ZEB1, BMPR2 was strongly negatively correlated with both Th1 cells and M1 macrophages, supporting an association with reduced pro-inflammatory cells within breast tumors." (PMID 31780722, 2019). "ACVR1C, TGFBR2, TGFBR3, ACVR2A, ACVR1, BMPR1A and BMPR2 were lower in breast tumours while ACVR1B and BMPR1B exhibited relatively higher expression levels in paired tumours compared with normal breast tissues, in the TCGA_BRCA cohort." (PMID 37333824, 2023).
Cirrhosis (2 papers, 2022 to 2023). A chronic disorder of the liver in which liver tissue becomes scarred and is partially replaced by regenerative nodules and fibrotic tissue resulting in loss of liver function. "Studies have also identified BMP9, shown to circulate at diminished levels in PoPH plasma as compared to non-PoPH cirrhosis, as able to rescue BMPR2 deficiency in animal models." (PMID 37558836, 2023). "PoPH samples demonstrated relatively more intense staining for both the ESR1 and FLT1 proteins, and relatively less staining for the BMPR2 protein, in the region surrounding liver central veins (the “peri-central” zone) relative to non-PoPH cirrhosis tissue." (PMID 37558836, 2023). "Differential gene expression analysis showed relative increase in ESR1 gene expression across multiple PoPH cell clusters, as well as decreased BMPR2 expression in PoPH hepatocytes, relative to liver from non-PoPH patients with cirrhosis." (PMID 37558836, 2023). "In this study, we observed differential gene expression of BMPR2, ESR1, and FLT1 genes in livers from patients with PoPH relative to non-PoPH cirrhosis, patterns supported by immunohistochemical staining of human liver tissue." (PMID 37558836, 2023). "In particular, BMPR2 expression appeared to be reduced, and both ESR1 and FLT1 expression appeared to be increased, in PoPH peri-central hepatocytes as compared to non-PoPH cirrhosis liver tissue." (PMID 37558836, 2023). "As PoPH nuclei demonstrated a pattern of differential gene expression involving the BMPR2, ESR1, and FLT1 genes, we then sought to validate this pattern of gene expression using immunohistochemistry staining of human liver tissue from PoPH, non-PoPH cirrhosis, and normal liver tissue samples." (PMID 37558836, 2023).
Eisenmenger syndrome (2 papers, 2022 to 2024). "More recently, a role for pathogenetic polymorphisms in PAH-CHD has been suggested: BMPR2 mutations were identified in 6% of adults and children with PAH-CHD (mainly Eisenmenger syndrome or post-repair), although the role of BMPR2 in PAH-CHD remains unclear." (PMID 38784170, 2024). "Of them, three had at least one P or LP variant: one patient with PAH after the closure of a ventricular septal defect (SOX17), one individual with PAH associated with incidental defects (ABCC8 and SMAD1), and the remaining one with a complex Eisenmenger syndrome (BMPR2)." (PMID 36142358, 2022). "We found a digenic likely pathogenic variant (ABCC8/ SMAD 1) in a case of coincidental PAH and several thoracic collaterals, a pathogenic variant in BMPR2 in a case of PAH after defect closure, and a pathogenic SOX17 variant in a patient with Eisenmenger syndrome." (PMID 36142358, 2022).
emphysema (2 papers, 2021 to 2023). "We also found the adipocyte-specific BMPR2 knockout mice to spontaneously develop lung injury and emphysema, in which adipsin and GDF5 might be involved in the pathogenesis." (PMID 37886639, 2023). "Our study utilized adipocyte-specific BMPR2 knockout mice and found that CKO mice presented with a COPD phenotype, with emphysema, lung injury, and arteriole remodeling." (PMID 37886639, 2023). "Therefore, BMPR2 might play a vital role in COPD-related lung injury and emphysema." (PMID 37886639, 2023).
heart failure (2 papers, 2016 to 2020). Inability of the heart to pump blood at an adequate rate to meet tissue metabolic requirements. "The pulmonary and heart failure might be involved in the death of BMPR2-knockout mice." (PMID 32350411, 2020).
Hyperglycemia (2 papers, 2019 to 2024). An increased concentration of glucose in the blood. "The characteristic increase in IL-6 during COVID-19 inhibits BMPR2, which normally protects against increased TGFβ signaling, and upregulated TGFβ1 contributes to hyperglycemia." (PMID 38674024, 2024).
insulin-dependent diabetes (2 papers, 2011 to 2019). "In addition, reduced Bmpr2 has been found in the kidney of type-1 diabetic rats." (PMID 30689673, 2019). "Similarly, downregulated lung Bmpr2 has also been found in a rat model of type 1 diabetes but not in the insulin-resistant OZR." (PMID 30689673, 2019).
leukemia (2 papers, 2023 to 2024). A malignant (clonal) hematologic disorder, involving hematopoietic stem cells and characterized by the presence of primitive or atypical myeloid or lymphoid cells in the bone marrow and the blood. "These efforts and additional validation experiments revealed PSIP1, CREBBP, and kinase FLT3 representing known vulnerabilities in KMT2A-r, as well as ARID4B, MBD3, and BMPR2 as potential candidates to be considered as novel therapeutic targets in this aggressive type of leukemia." (PMID 37686014, 2023).
lymph node metastasis (2 papers, 2021 to 2023). "Furthermore, BMPR1A, BMPR1B, and BMPR2 were associated with clinical factors, including age, ethnicity, tumor size, and lymph node metastasis." (PMID 34036102, 2021). "In addition, the expression of BMPR2 was also significantly correlated with lymph node metastasis (p = 0.002)." (PMID 36460803, 2023).
malignant glioma (2 papers, 2012 to 2017). A grade III or grade IV glioma arising from the central nervous system. "It is known that miR-135a can function as a selective killer of malignant glioma by targeting STAT6, SMAD5 and BMPR2." (PMID 28415713, 2017).
Myocardial fibrosis (2 papers, 2021 to 2022). "This balance and the unaltered levels of phosphorylated SMAD2/3 are also in line with the absence of myocardial fibrosis, as BMPR2 is an antagonist in the TGFβ fibrotic pathway, preventing fibrosis." (PMID 33716758, 2021).
osteonecrosis (2 papers, 2021 to 2022). A none disease characterized by death of bone tissue due to a lack of blood supply. "In nontraumatic osteonecrosis of the femoral head, miR-100-5p inhibited the BMPR2-Smad1/5/9 signaling pathway by reducing the expression of BMPR2 and destroying the bone formation of hBMSCs." (PMID 36064455, 2022). "The NONFH exosomal miR-100-5p can lead to NONFH-like damage by targeting BMPR2 and suppressing the BMPR2/SMAD1/5/9 signalling pathway, which may be involved in the pathophysiological mechanisms of nontraumatic osteonecrosis of the femoral head (NONFH)." (PMID 34256859, 2021).
sarcoma (2 papers, 2016 to 2017). A usually aggressive malignant neoplasm of the soft tissue or bone. "To discount prognostic influences of BMPR1A, BMPR1B or BMP2 expression individually, we constructed Kaplan-Myer curves for the entire sarcoma dataset and compared patients with the highest and lowest 10% expression of BMPR1A, BMPR1B, BMPR2, BMP2 and BMP7." (PMID 27114889, 2016). "As no influence of BMPR2 levels on osteo-sarcoma cells’ proliferation, it was interesting to examine whether BMPR2 affected the migration and invasion of 143B and U2OS cells." (PMID 28938584, 2017).
thyroid (2 papers, 2018 to 2022). "Lastly, thyroid diseases have been associated with mutations in the gene encoding the bone morphogenetic protein receptor type II (BMPR2), a well described genetic cause of PAH." (PMID 35207198, 2022). "Thus, the increased BMPR2 expression we found in our study could be paired with a decrease in the expression of the TGF‐β1, something that has been demonstrated for patients with GD in a recent study carried out in biopsy samples from thyroid pathology patients." (PMID 29266775, 2018).
viral infection (2 papers, 2020). "Upon viral infection, BMPR2 gets suppressed which result inhibition of pulmonary vascular homeostasis." (PMID 32802902, 2020).
acute myeloid leukemia (1 paper, 2019). Acute myeloid leukemia (AML) is a group of neoplasms arising from precursor cells committed to the myeloid cell-line differentiation. "In acute myeloid leukemia, SPG6 supported development of acute myeloid leukemia by regulating BMPR2-Smad-Bcl-2/Bcl-xl signaling." (PMID 31889906, 2019).
aneurysm (1 paper, 2022). Bulging or ballooning in an area of an artery secondary to arterial wall weakening. "A research has shown that mutations of BMPR2 can cause the Loeys-Dietz syndrome, which is an inherited connective tissue disorder can accompanied with aneurysms." (PMID 35209959, 2022).
arteriosclerosis (1 paper, 2019). A vascular disorder characterized by thickening and hardening of the walls of the arteries. "BMPR2 expression levels are regulated beyond genetic factors, and low expression is found in IPAH but also a variety of other vascular diseases, including arteriosclerosis." (PMID 31826007, 2019).
B-cell lymphoma (1 paper, 2014). "Little is known about the expression correlation between BMPR2 and TNFAIP3 genes in B-cell lymphoma." (PMID 25364581, 2014). "Additionally, in the different B-lymphocyte malignant cell lines, the expression levels of BMPR2, EP300, TGFβ2, and TNFAIP3 mRNA were quite different, which may be related to the heterogeneity of B-cell lymphoma." (PMID 25364581, 2014).
colitis (1 paper, 2013). Inflammation of the colon. "Several studies have supplied supporting evidence to the current findings indicating an upregulation of BMPR2 expression at 2 days following BMP-7 administration in various models including TNBS-induced colitis." (PMID 24376781, 2013).